ALKAL2 (ALK and LTK ligand 2)
Description:
Cytokine that acts as a physiological ligand for receptor tyrosine kinases LTK and ALK, leading to their activation. Cytokine-binding is sufficient to activate LTK. In contrast, ALKAL2-driven activation of ALK is coupled with heparin-binding to ALK. Stimulation of ALK signaling is involved in neural development and regulation of energy expenditure.
Synonyms: FAM150B; AUGA; PRO1097; RGPG542
Tractability: Antibody: UniProt places it where antibodies can reach, with high confidence; its Gene Ontology location is reachable by antibodies, with high confidence; UniProt predicts a signal peptide or a membrane-spanning region.
Gene: Protein-coding gene on chromosome 2 (278,286 to 289,623, reverse strand). Ensembl gene ENSG00000189292.
Subcellular location: Secreted; Cell membrane
Pathways (Reactome):
Signal Transduction: Signaling by ALK; Signaling by LTK
Gene Ontology:
Molecular function: cytokine activity; protein binding; receptor signaling protein tyrosine kinase activator activity; receptor tyrosine kinase binding
Biological process: cell surface receptor protein tyrosine kinase signaling pathway; positive regulation of ERK1 and ERK2 cascade; positive regulation of ERK5 cascade; positive regulation of neuron projection development
Cellular component: extracellular region; plasma membrane
Genetic constraint (gnomAD): Loss-of-function variants: 6 observed, 9.11 expected, observed/expected ratio (o/e) 0.66, 90% interval 0.36 to 1.3. That is too few expected variants to judge how well the gene tolerates losing a copy. Missense variants: 220 observed, 145.64 expected, observed/expected ratio (o/e) 1.51, 90% interval 1.35 to 1.69. Synonymous variants: 125 observed, 68.95 expected, observed/expected ratio (o/e) 1.81, 90% interval 1.56 to 1.97.
Homologues: Orthologues: chimpanzee ALKAL2 (99% identical), macaque ALKAL2 (99% identical), rabbit ALKAL2 (79% identical), pig ALKAL2 (76% identical), mouse Alkal2 (75% identical), guinea pig ALKAL2 (72% identical), dog ALKAL2 (71% identical), rat Alkal2 (66% identical), tropical clawed frog alkal2 (45% identical), zebrafish alkal2b (45% identical), zebrafish alkal2a (40% identical).
Diseases named in the same sentence as ALKAL2 in open-access papers:
ALKAL2 is named in the same sentence as 12 diseases in open-access papers, as found by Europe PMC text mining. Sharing a sentence is not in itself a finding about the gene and the disease. The quoted sentences say what the papers report.
neuroblastoma (10 papers, 2015 to 2025). Neuroblastoma (NB) is the most common solid, extracranial childhood tumor. "Previous studies also reported that ALKAL2 was able to activate ALK in vivo and coexpression of ALKAL2 with ALK was found to promote neurite outgrowth in neuroblastoma cell lines." (PMID 35608912, 2022). "The ALK gene is situated in proximity to MYCN and ALKAL2 on chromosome 2p and it has been argued that co-amplification of these three explains the inferior outcome in neuroblastoma patients with 2p gain." (PMID 35362827, 2022). "What happens in neuroblastoma when the troika of ALKAL2, ALK, and MYCN are aberrantly expressed, or activated, in either 2p-gain or amplification?" (PMID 34885007, 2021). "The original reports of ALKAL activation of ALK noted that ALKAL2 was expressed in the adrenal glands and that its expression was observed in neuroblastoma patient samples." (PMID 34885007, 2021). "The oncogenic mechanism in neuroblastoma operates by activation of RAS-MAPK-ERK and other downstream pathways, and can be initiated by activating mutations of ALK, ALK amplifications, or, possibly, changes to the ALK ligands ALKAL1 and ALKAL2." (PMID 35362827, 2022). "Two recent studies have further addressed a potential function of ALKAL2 in neuroblastoma." (PMID 34885007, 2021). "Here, evaluation of ALKAL2 levels in neuroblastoma could provide a potential biomarker for ALK signaling activity that is not captured by genetic mutation analysis." (PMID 34885007, 2021). "Furthermore, they showed that neuroblastoma cell lines express ALKAL2 protein, identifying a potential autocrine/paracrine activation of ALK in a tumor setting." (PMID 34885007, 2021).
Arthritis (1 paper, 2022). Inflammation of a joint. "Given the relationship between the sympathetic and nociceptive systems, it will be important to determine whether upregulation of ALKAL2 in the DRG neurons promotes sympathetically maintained pain in the context of arthritis or neuropathic pain." (PMID 35608912, 2022).
glioblastoma (1 paper, 2021). The most malignant astrocytic tumor (WHO grade IV). "However, the increased levels of VGF observed in both ALKAL2‐ and ALK‐F1178S‐driven NB are of interest given a recent report that VGF expression in glioblastoma promotes tumour survival and growth." (PMID 33411331, 2021).
Nephropathy (1 paper, 2023). A nonspecific term referring to disease or damage of the kidneys. "The SH3YL1 gene has recently been implicated as a biomarker for nephropathy in type 2 diabetes, whereas ALKAL2 enables protein tyrosine kinase activity." (PMID 36975205, 2023).
cancer (7 papers, 2019 to 2025). A tumor composed of atypical neoplastic, often pleomorphic cells that invade other tissues. "ALKAL2, also named augmentor-α (AUG-α) or FAM150b, was first described in the adrenal gland and the retina, where its signaling through ALK and LTK receptors has been implicated in autoimmunity, neurodevelopment, and cancer." (PMID 35608912, 2022). "Currently, although mutations in the ALKAL2 locus are found in cancer sequence cohorts, these have not been explored and none have been reported as having an impact on NB development." (PMID 33411331, 2021). "Indeed, the employment of ALK neutralizing antibody rather than TKI may represent a successful strategy to block the ALKAL2/ALK autocrine loop driving cancer growth in patients that currently have very limited treatment options." (PMID 35351152, 2022). "Activation of Anaplastic lymphoma kinase (ALK) and leukocyte tyrosine kinase (LTK) by their cognate cytokines ALKAL2 and ALKAL1 plays important roles in development, metabolism, and cancer." (PMID 40208865, 2025). "Stemming from these observations, we propose a model in which an autocrine loop of ALKAL2-mediated ALK activation, by signaling through the AKT downstream cascade, is responsible for the CMS1 cancer progression." (PMID 35351152, 2022). "Moreover, the PI3K-AKT pathway has been validated as the downstream signaling pathways of ALKAL2-ALK signaling and PDGFA-PDGFRB signaling in human cancers." (PMID 38812530, 2024). "ALKAL2 misregulation facilitates ALK receptor tyrosine kinase signaling and drives ALK‐dependent cancer irrespective of oncogenic mutations." (PMID 33411331, 2021).
tumours (4 papers, 2019 to 2025). "Tumours also expressed ALKAL2 protein, in keeping with our previous findings of ALKAL2 protein in human NB cells." (PMID 33411331, 2021). "Analysis of Alkal2‐ and Alk‐F1178S‐induced mouse tumours at the DNA level led to the detection of very few genetic alterations." (PMID 33411331, 2021). "At the molecular level, our data identified robust upregulation of VGF in both ALKAL2‐driven NB cell lines and mouse tumours, a finding also noted by Cazes and coworkers." (PMID 33411331, 2021). "The expression of Chga, Th, Dbh, Syp, Ncam1 and Alkal2 was also observed in the tumour transcriptome of all three genotypes (Table EV4), which is in agreement with our histological analysis." (PMID 33411331, 2021). "ALKAL2‐induced tumours were further investigated by RNA‐Seq analysis." (PMID 33411331, 2021). "Moreover, analysis of NB cell lines and tumour samples has highlighted expression of ALKAL2 mRNA and protein in NB." (PMID 33411331, 2021). "Cell line #3456 was generated from an Alk‐F1178S;Th‐MYCN NB, while cell line #3540 was generated from Rosa26_Alkal2;Th‐MYCN tumour tissue." (PMID 33411331, 2021). "It is interesting that the ALKAL2‐induced transcriptomic response observed in Rosa26_Alkal2;Th‐MYCN is weaker than that seen in Alk‐F1178S;Th‐MYCN tumours." (PMID 33411331, 2021). "The ALK ligand ALKAL2 can be secreted by adrenocortical-like stromal cells within NB tumours but not by cancer neuroblasts themselves." (PMID 41511287, 2025). "Similar to Alk‐F1178S, no gross tumour development was observed in mice carrying the Rosa26_Alkal2 transgene alone." (PMID 33411331, 2021). "To test whether ALKAL2‐driven NB was sensitive to ALK TKI treatment in vivo, we treated NB tumours arising in Rosa26_Alkal2;Th‐MYCN mice with lorlatinib (10 mg/kg body weight, 2× per day) for a period of 14 days and monitored tumour growth by ultrasound." (PMID 33411331, 2021). "To investigate whether ALKAL2‐driven NB is sensitive to ALK TKI treatment, we first established murine NB cell lines from tumours harvested from Rosa26_Alkal2;Th‐MYCN and Alk‐F1178S;Th‐MYCN mice." (PMID 33411331, 2021). "This raises the possibility that NB tumours with 2p gain may instead benefit from extra copies of MYCN and ALK wildtype receptor in collaboration with its recently described ligand, ALKAL2 located at 2p25." (PMID 30778092, 2019). "This suggests that in tumours with high ALK expression but lacking ALK mutations, oncogenic signalling may be driven by microenvironmental ligands such as ALKAL2, potentially derived from the adrenal medulla." (PMID 41511287, 2025).
infection (1 paper, 2022). The state of being infected such as from the introduction of a foreign agent such as serum, vaccine, antigenic substance or organism. "While future studies are warranted for determining whether neuronal ALKAL2 participates in the inflammatory response, it is plausible that, upon activation, peptidergic TRPV1 nerve endings release ALKAL2 at the periphery, thus contributing to skin and mucosal host responses to infection or injury." (PMID 35608912, 2022).
ALKAL2 also shares sentences with these, for which no sentence is quoted: Obesity (2 papers); autoimmune disease (1); breast carcinoma (1); colon cancer (1); type 2 diabetes (1).